LEP (leptin)
Diseases named in the same sentence as LEP in open-access papers (continued):
Sharing a sentence is not in itself a finding about the gene and the disease.
ulcer (3 papers, 2015 to 2021). "Regardless of the success or failure of H. pylori eradication, presumably, the suppressed appetite of peptic ulcer patients improved with the healing of the ulcer, which led to increased food intake and increased plasma leptin levels as a consequence." (PMID 27716077, 2016). "In rats with ulcers, leptin treatment (10 μg/kg BW) supports ulcer healing via production of nitric oxide (NO) and histamine, suppression of oxidative stress, and enhanced expression of transforming growth factor-α (TGF-α), a critical growth promoting factor for the gastric mucosa." (PMID 33935782, 2021). "Histometric analysis of dermal connective tissue revealed that more CD31-positive cells, i.e. more blood vessels, were observed in the connective tissue beneath the ulcer area in the leptin-treated group compared with the control group at day 8 after would creation." (PMID 25799398, 2015).
Uterine leiomyoma (3 papers, 2021 to 2025). The presence of a leiomyoma of the uterus. "Activation of JAK2/STAT3, MAPK/ERK, and PI3k/Akt pathways have previously been linked to the binding of leptin, an adipocyte derived hormone, to Ob-R; however, the effect of adipocyte coculture on uterine leiomyoma cells remained a gap in knowledge." (PMID 36771423, 2023). "We further investigated the potential role of leptin in the inflammation, angiogenesis, and fibrosis in human uterine leiomyoma and myometrium cells." (PMID 36771423, 2023). "Human uterine leiomyoma (HuLM) cells responded more to leptin treatment compared to myometrium cells with increased secretion of inflammatory factors: IFNγ, IL-6, IL-8, MCP-1, GM-CSF, and TNF-a." (PMID 36771423, 2023). "For the first time, we demonstrated the amplified activation of JAK2/STAT3, MAPK/ERK, and PI3k/Akt because of adipocyte coculture along with leptin treatment in uterine leiomyoma cells." (PMID 36771423, 2023). "Until now, solely serum leptin levels in patients with uterine leiomyomas have been studied, but the data is inconsistent." (PMID 34399708, 2021). "Therefore, we sought to investigate whether leptin has any impact on pro-fibrotic and angiogenic mediators, specifically in the context of uterine leiomyomas." (PMID 36771423, 2023).
uveitis (3 papers, 2007 to 2024). An inflammatory process affecting a part of or the entire uvea. "A larger case series is necessary to investigate serum Hcy and leptin concentrations in uveitis patients." (PMID 27800222, 2015). "The results of our study alsodemonstrated that the mean serum leptin levels were significantly increased in patients withactive uveitis compared to control subjects." (PMID 17641728, 2007). "However, there might be a correlationbetween leptin levels and uveitis activity." (PMID 17641728, 2007).
varicocele (3 papers, 2010 to 2022). A condition characterized by the dilated tortuous veins of the spermatic cord with a marked left-sided predominance. "For instance, the level of leptin in the semen of varicocele patients was significantly higher than that in the normal subjects." (PMID 36187750, 2022). "The seminal leptin content was positively correlated with varicocele classification and inversely proportional to sperm motility." (PMID 36187750, 2022). "They showed that patients with varicocele (VC [leptin] = 3.2 ng/mL) and leukocytospermia (LC [leptin] = 2.72 ng/mL) had high concentrations of seminal leptin as well as increased ROS (reactive oxygen species) and apoptosis compared to the control group." (PMID 29971101, 2018).
vasculitis (3 papers, 2010 to 2016). "In contrast to our results, this study showed that active anti-neutrophil cytoplasmic antibody (ANCA)-associated vasculitis is characterized by increased serum ghrelin and decreased serum leptin, both of which return to normal with successful therapy." (PMID 23259466, 2012).
3-M syndrome (2 papers, 2013 to 2024). 3M syndrome is a primordial growth disorder characterized by low birth weight, reduced birth length, severe postnatal growth restriction, a spectrum of minor anomalies (including facial dysmorphism) and normal intelligence. "Downregulation of leptin in 3-M syndrome may represent a response to the patients slim body habitus or be a signal to drive energy intake in order to promote growth." (PMID 24148222, 2013).
abortion (2 papers, 2016 to 2020). the ending of pregnancy by removing a fetus or embryo before it can survive outside the uterus. "In our study, plasma leptin was measured during early pregnancy prior to the occurrence of the spontaneous abortion." (PMID 32244842, 2020). "Regarding the adipokines leptin and adiponectin, we could not detect any difference between controls and spontaneous abortion." (PMID 32244842, 2020).
acquired lipodystrophy (2 papers, 2019 to 2022). An instance of lipodystrophy (disease) that is acquired during the lifetime of the individual. "The form of leptin currently available to humans is recombinant methionyl human leptin, or metreleptin, which has been recently approved by the US Food and Drugs Administration (FDA) for treating generalized congenital or acquired lipodystrophy." (PMID 31067764, 2019).
acute leukemia (2 papers, 2022 to 2023). A clonal (malignant) hematopoietic disorder with an acute onset, affecting the bone marrow and the peripheral blood. "When including BMI or Adiponectin together with Leptin into the Cox regression, an independent, significant, prognostic effect of Leptin in higher risk acute leukemia remained, underlining the novel and is a unique characteristic of this marker." (PMID 35216457, 2022). "Here, low pre-conditioning serum Leptin levels are identified to be a prognostic marker of early relapse in Acute Leukemia patients of intermediate and advanced stage disease following alloSCT." (PMID 35216457, 2022).
acute lung injury (2 papers, 2023 to 2025). A condition of lung damage that is characterized by bilateral pulmonary infiltrates (pulmonary edema) rich in neutrophils, and in the absence of clinical heart failure. "Conflicting animal studies on leptin's role in acute lung injury (ALI) further complicate its understanding, with some showing protection and others increased susceptibility to lung damage." (PMID 40635334, 2025).
acute promyelocytic leukemia (2 papers, 2021 to 2025). An aggressive form of acute myeloid leukemia (AML), characterized by arrest of leukocyte differentiation at the promyelocyte stage, due to a specific chromosomal translocation t(15;17) in myeloid cells. "AnxA8 levels are upregulated by leptin, during mammary gland involution and in acute promyelocytic leukemia (APL) cells." (PMID 33810523, 2021).
alopecia (2 papers, 2022 to 2024). Hair loss usually from the scalp. "Scd1 was initially identified in the ‘asebia’ mouse that has a naturally occurring mutation in the Scd1 gene and exhibits alopecia, sebocyte hypoplasia, and resistance to leptin deficiency induced obesity." (PMID 38565895, 2024).
amoebiasis (2 papers, 2018 to 2021). "Leptin-mediated specific activation of STAT3 and ERK or Akt signaling pathways in gut mucosal epithelial cells offers more resistance against amoebiasis caused by E. histolytica infection." (PMID 30534129, 2018).
anaplastic thyroid cancer (2 papers, 2016 to 2017). "In anaplastic thyroid cancer cells, leptin induced the expression of MMP2, and MMP9 which are involved in the invasion of cancer cells." (PMID 27050378, 2016). "In order to determine if leptin/OB3 activated signal transduction in anaplastic thyroid cancer cells, cells were treated with OB3 (10 μM) or leptin (0.625 μM) for 4 h." (PMID 27050378, 2016). "In summary, leptin in anaplastic thyroid cancer cells not only increased expression of MMP2, MMP9 and VEGF in the current studies, supporting angiogenesis, but also induced cancer cell invasiveness and reduced adhesion." (PMID 27050378, 2016). "The ability of anaplastic thyroid cancer cells to invade was remarkably increased when they were treated with leptin." (PMID 27050378, 2016). "Leptin not only stimulated expression of genes involved in invasion, but also promoted invasion in the Transwell assay in anaplastic thyroid cancer cells." (PMID 27050378, 2016). "Our results demonstrate that leptin stimulates invasiveness and reduced adhesion of anaplastic thyroid cancer cells." (PMID 27050378, 2016). "In anaplastic thyroid cancer cells, leptin reduced the expression of integrin β3 significantly and increased integrin αv significantly." (PMID 27050378, 2016). "In anaplastic thyroid cancer cells, leptin stimulated cell invasion, but reduced adhesion." (PMID 28750624, 2017). "Leptin stimulated cell invasion, but reduced adhesion in anaplastic thyroid cancer cells." (PMID 27050378, 2016). "On the other hand, leptin enhanced cell migration and invasion in anaplastic thyroid cancer cells." (PMID 27050378, 2016). "Phosphorylation of Tyr-705 of STAT3 is induced by leptin and OB3 in anaplastic thyroid cancer cells." (PMID 28750624, 2017). "Both OB3 and leptin reduced PCNA expression significantly and increased the expression of c-Myc and MCL-1 slightly in anaplastic thyroid cancer cells." (PMID 27050378, 2016). "Interestingly, both leptin and OB3 reduced the activation of FAK in anaplastic thyroid cancer cells." (PMID 27050378, 2016). "When anaplastic thyroid cancer cells were treated with leptin in the presence or absence of specific signal transduction pathway inhibitors PD98059, LY294002 and an inhibitor of STAT3, S31-201, the leptin-induced cell invasion was inhibited by PD and S31-201, but not LY294002." (PMID 27050378, 2016). "Indeed, pharmacologic inhibition of ERK1/2 and STAT3, but not PI3K, signaling inhibited leptin-induced invasion in anaplastic thyroid cancer cells." (PMID 27050378, 2016). "However, the expression of VEGF, a principal contributor to angiogenesis, was enhanced by leptin but not OB3 in anaplastic thyroid cancer cells." (PMID 27050378, 2016). "In addition, phosphorylation of Tyr-705 in STAT3, but not Ser-727, was induced by leptin and OB3 in anaplastic thyroid cancer cells." (PMID 27050378, 2016).
Anosmia (2 papers, 2017 to 2020). An inability to perceive odors. "The reported anosmia in SARS-CoV-2 disease may also be partly explained by leptin since elevated levels of leptin are thought to alter the olifactory epithelium." (PMID 32844126, 2020).
aortic stenosis (2 papers, 2024 to 2025). Aortic valve stenosis is a aortic valve disease caused by the incomplete opening of the aortic valve. "Notably, this relationship appears to be sex-specific, with variations in the leptin concentrations observed between men and women diagnosed with aortic stenosis." (PMID 39335491, 2024). "However, considering only patients with severe aortic stenosis, a significant and pronounced correlation was noted with increased leptin levels." (PMID 39335491, 2024). "This meta-analysis aims to evaluate the relationships between adiponectin and leptin levels and FCAVD, particularly in patients with severe aortic stenosis (AS)." (PMID 39335491, 2024).
aortic valve calcification (2 papers, 2024 to 2025). "Our meta-analysis showed that, while adiponectin and leptin are both implicated in cardiovascular pathologies, their roles in fibro-calcific aortic valve disease appear to be distinct." (PMID 39335491, 2024).
autoimmune hepatitis (2 papers, 2019 to 2023). Hepatitis caused by autoantibodies. "These animals are hyperphagic and morbidly obese, but, in contrast to other leptin or LR-deficient rodents, display only minimal changes in size and cellularity of the thymus and respond to concavalin A in a model for autoimmune hepatitis." (PMID 30659329, 2019). "Increased serum Leptin has also been identified as a negative prognostic factor for the response to steroid therapy in autoimmune hepatitis." (PMID 37744450, 2023).
B-cell lymphoma (2 papers, 2005 to 2022). "Leptin also increases expression of matrix metalloproteinases and tissue inhibitors of metalloproteinases, which are associated with aggressive disease, neoplastic growth and angiogenesis in B-cell lymphomas." (PMID 16160698, 2005). "Interestingly, some of these genes, such as LEP, ALOX12, RARRES2, DLEU7, and FOXR1, have been reported to be associated with other hematologic malignancies, including AML, chronic lymphocytic leukemia (CLL), and B-cell lymphoma." (PMID 35847864, 2022).
blood pressure (2 papers, 2019 to 2022). "SSB intake was associated with higher blood pressure in girls, and with biomarkers of glycemia (C-peptide, CP-IR, leptin) and fat distribution (waist circumference, skinfold thicknesses) in boys." (PMID 31108933, 2019). "In an animal model, mice that overexpressed leptin had high blood pressure and increased catecholamine excretion in their urine." (PMID 36619557, 2022).
bone metabolism disorders (2 papers, 2008 to 2016). "Four genes are proposed as markers for cardiovascular as well as bone metabolism disorders, namely the PTH, the TNF, leptin (LEP), as well as IL-6." (PMID 18266955, 2008).
cardiac arrest (2 papers, 2020 to 2021). Cessation of breathing and/or cardiac function. "Cardiac arrest and ECPR markedly increased the plasma levels of IL-10, VEGF, leptin, TNF-α, IL-1β, IL-6, fractalkine, IL-5, IL-18, IP-10, IL-4, eotaxin, MIP-1α, IL-17α, IL-12, RANTES, G-CSF, LIX, and MCP-1." (PMID 34781966, 2021). "To this end, we measured the plasma levels of four adipokines (adiponectin, leptin, fatty acid-binding protein 4 (FABP4), and visfatin) in 21 cardiac arrest patients at the admission and 2 or 7 days post ROSC." (PMID 32015774, 2020). "In the present study, we measured the plasma levels of four adipokines (adiponectin, leptin, fatty acid-binding protein 4 (FABP4), and visfatin) in cardiac arrest patients following return of spontaneous circulation (ROSC)." (PMID 32015774, 2020).
centripetal obesity (2 papers, 2017 to 2025). "On one hand, this is significantly related to hormonal fluctuations that cause abnormal appetite regulation (such as leptin resistance) and changes in fat distribution (centripetal obesity)." (PMID 41334401, 2025).
cholera (2 papers, 2015 to 2016). "Despite these limitations, our study of 74 children with cholera in Bangladesh suggests an association of plasma leptin levels and cholera and an association of leptin with immune responses during cholera." (PMID 26055740, 2015). "Our results suggest that leptin levels may be associated with cholera, including the development of immune responses to T cell–dependent antigens." (PMID 26055740, 2015). "We also did not assess leptin levels in children prior to their becoming symptomatic with cholera, so we cannot comment on whether leptin levels affect the risk of cholera or change significantly with onset of acute disease." (PMID 26055740, 2015). "Association of leptin levels with immune responses to cholera." (PMID 26055740, 2015). "We found that leptin levels are low during the acute stage of cholera compared with levels in healthy matched controls and that plasma leptin levels rise following cholera during late convalescence." (PMID 26055740, 2015). "We then assessed immune responses to V. cholerae antigens in 74 children with cholera, correlating these responses to plasma leptin levels on day 2 of illness." (PMID 26055740, 2015). "We found that patients at the acute stage of cholera had significantly lower plasma leptin levels than matched controls, and compared with levels in late convalescence." (PMID 26055740, 2015). "We characterized leptin levels in 11 children with cholera in Bangladesh, assessing leptin levels on days 2, 7, 30, and 180 following cholera." (PMID 26055740, 2015). "Our data also suggest that leptin plays a role in the development of antibody responses to cholera antigens." (PMID 26055740, 2015). "We also found the same trend of reduced leptin levels in all 74 participants (47% of the participants were female, 53% were male) within the acute phase of cholera (days 2 and 7) in comparison to day 30 and healthy controls." (PMID 26055740, 2015). "Leptin levels during acute cholera were low and stayed suppressed for at least 1 month after recovery; leptin concentrations on day 2 were related to immunoglobulin G antibody levels to cholera toxin 30 days later, indicating the impact of leptin on immune function." (PMID 26967147, 2016). "Similarly, since anthropometric measurements were not performed at day 180 in this study, we cannot answer whether the rise in plasma leptin levels in cholera patients by late convalescence reflected recovery from cholera or improvement in nutritional status of affected children." (PMID 26055740, 2015). "We also only assessed leptin levels in plasma and not in intestinal tissue during cholera, and our sample size is also relatively small, especially when considering children by various nutritional categories." (PMID 26055740, 2015). "When we compared plasma leptin levels in these 11 cholera patients to age, gender, and nutritionally (WAZ) matched controls, we found that the plasma leptin levels during the acute phase of cholera (days 2 and 7) were significantly lower than the levels in non-cholera matched controls (P < 0.05)." (PMID 26055740, 2015).
chronic hepatitis B (2 papers, 2007 to 2017). "In view of the obscure role of serum leptin in CVH we were interested in its role in chronic hepatitis B (CHB) and CHC infection." (PMID 17540037, 2007).
cyst (2 papers, 2016 to 2023). A sac-like closed membranous structure that may be empty or contain fluid or amorphous material. "The levels of leptin, adiponectin, and resistin were significantly lower in breast cyst fluid than in plasma regardless of the cyst type." (PMID 27293305, 2016).
dental caries (2 papers, 2022 to 2023). The decay of a tooth, in which it becomes softened, discolored, and/or porous. "Consistent gradients were observed in mean values for BMI, waist circumference, leptin levels, c‐reactive protein, white blood cell count and the pace of aging by dental caries experience at age five." (PMID 37920118, 2023). "It has been reported that dental caries severity increased with higher levels of salivary ghrelin and lower levels of salivary leptin." (PMID 36120658, 2022).
dermatomyositis (2 papers, 2015 to 2016). Dermatomyositis (DM) is a type of idiopathic inflammatory myopathy characterized by evocative skin lesions and symmetrical proximal muscle weakness. "Moreover, increased serum adiponectin and resistin levels were detected in dermatomyositis patients, but lower serum leptin levels were observed." (PMID 28076515, 2016). "To investigate the role of adipokines in adult and pediatric patients with newly diagnosed dermatomyositis (DM), we analyzed peripheral blood and skeletal muscle gene expression of four adipokines: visfatin, leptin, adiponectin and resistin." (PMID 25918482, 2015).
developmental delay (2 papers, 2013 to 2024). "Our previous work on the IUGR piglet showed that neonatal leptin supplementation corrected the developmental delay and adjusted the growth of several organs such as the pancreas, liver and lung to levels similar to those observed in normal birth BW animals." (PMID 23741353, 2013).
diabetic cardiomyopathy (2 papers, 2016 to 2024). Diabetic cardiomyopathy is a disorder of the heart muscle in people with diabetes. "Smad3 null mice crossed with leptin deficient db/db diabetic mice were protected from the development of diabetic cardiomyopathy." (PMID 26925344, 2016).
ductal carcinoma (2 papers, 2020 to 2021). "However, a growing ductal carcinoma induces a significant expression of leptin as a major proliferative factor in the surrounding normal breast tissue, suggesting a possible role of leptin in disease progression." (PMID 34588926, 2021).